PDCD4 (programmed cell death 4)
Diseases named in the same sentence as PDCD4 in open-access papers (continued):
Sharing a sentence is not in itself a finding about the gene and the disease.
breast cancer (continued). "These investigators subsequently showed that miR-21 regulated breast cancer metastasis by down regulating tumor suppressor genes, such as programmed cell death 4 (PDCD4) and maspin." (PMID 23272133, 2012). "miR-21 has been shown to down-regulate PDCD4, leading to an increase in cell proliferation, invasion, metastasis, and neoplastic transformation of breast cancer lesions." (PMID 20831814, 2010). "PDCD4 levels were also decreased in primary patient tumor samples from lung cancer, hepatocellular carcinoma, breast carcinoma, colon cancer, glioma, pancreatic cancer and esophageal carcinoma." (PMID 20831814, 2010). "A study in breast cancer cell line demonstrated knockdown of Pdcd4 significantly reduced the sensitivity to geldanamycin and tamoxifen." (PMID 19728867, 2009). "In breast cancer a decreased expression of PDCD4 was observed in comparison to normal breast tissue." (PMID 19473551, 2009). "Stable expression of antisense Pdcd4 significantly reduced the sensitivity of MCF-7 breast cancer cells to geldanamycin and to tamoxifen." (PMID 19728867, 2009). "Since we could not find a previous report about the presence of PDCD4 in CTCs, we confirmed PDCD4 in CTCs of breast cancer patients in our work." (PMID 39890941, 2025). "Our integrative analysis suggests that PDCD4 may also be involved in the EMT pathway during breast cancer development, a hypothesis that warrants further validation through experimental studies." (PMID 40567015, 2025). "Meanwhile, PDCD4 has been reported to regulate the proliferation and viability of other type of cells, including human peritoneal mesothelial cells, ovarian cancer cells and human breast cancer cells." (PMID 40003924, 2025). "PDCD4 is a well-characterized tumor suppressor in breast cancer." (PMID 39667501, 2025). "We next investigated the presence of PDCD4 in CTC of breast cancer patients." (PMID 39890941, 2025). "miR-21 may inhibit the growth and metastasis of luminal-like breast cancer by inhibiting the NF-κB/PDCD4 axis." (PMID 39057685, 2024). "In addition, Hypoxia-induced miR-424 targets the apoptosis-related tumor suppressor PDCD4, rendering breast cancer cells resistant to chemotherapies such as doxorubicin and etoposide." (PMID 37583933, 2023). "Furthermore, SKP2, an oncogene, promotes breast cancer tumorigenesis and radiation resistance through PDCD4 ubiquitination." (PMID 36826085, 2023). "According to the previous literature, Andrographolide inhibits the expression of NF-κB, and as a result, reduces the expression of miR-21-5p, dramatically increasing the target gene expression of programmed cell death protein 4 (PDCD4) to induce apoptosis in breast cancer." (PMID 37298343, 2023). "Notably, miR-424 expression negatively correlates with that of PDCD4 in clinical samples of breast cancer as well." (PMID 37583933, 2023). "The function of nuclear HER2 could be directed by STAT3, which recruits HER2 to activate the expression of miRNA-21 that in turn down-regulates the expression of the metastasis suppressor protein programmed cell death 4 (PDCD4) in breast carcinoma." (PMID 36459290, 2023). "Additionally, TargetScan predicts that Protein Phosphatase 4 Catalytic (PP4C) and Programmed Cell Death 4 (PDCD4) are direct targets of miR-27a, both of which have been directly correlated with migratory functions of breast cancer cell lines." (PMID 35110406, 2022). "Moreover, miR-21 represses the expression of the programmed cell death 4 (PDCD4) tumor suppressor protein in breast cancer cells." (PMID 35327559, 2022). "In this regard, PDCD4 expression in breast cancer cells could thus be regulated by non-coding RNAs, ubiquitin-proteasome activity, and inflammation." (PMID 36552834, 2022).
breast cancer (continued). "Other studies have demonstrated the positive efficacy of andrographolide, for example, andrographolide can down-regulate Mir-21-5p by targeting NF-κB, promote the expression of the PDCD4 target gene, and further inhibit the growth and metastasis of metastatic luminal breast cancer." (PMID 36177361, 2022). "Another miR-21 target, PDCD4, also induces apoptosis in breast cancer." (PMID 34202777, 2021). "This interesting role in breast cancer may be due to the inhibition of TGF-β with subsequent activation of programmed cell death 4 (PDCD4), decrease of MMP-3 and MMP-9 and increase of cell adhesion." (PMID 34884877, 2021). "Furthermore, miR-21-5p/PDCD4 signaling has been reported to be involved in paclitaxel-resistant breast cancer cells." (PMID 34249905, 2021). "As a key regulator of osteoclast, the expression level of PDCD4 was significant lower in osteoclasts treated with exosomes derived from breast cancer cell, indicating exosomal miR-21 was likely to regulate the establishment of metastatic niche via directly targeting PDCD4." (PMID 33391543, 2021). "In conclusion, hsa_circ_0053063 inhibits breast cancer cell proliferation via hsa_circ_0053063/hsa-miR-330-3p/PDCD4 axis, which may provide a new therapeutic target for BC patients." (PMID 33744861, 2021). "It has also been reported that miR-21 promotes invasion and cell proliferation by targeting programmed cell death 4 (PDCD4); miR-139 has been reported to act as a tumor suppressor in several cancer types, such as prostate cancer, endometrial cancer, and breast cancer." (PMID 33440868, 2021). "Mechanically, breast cancer-derived exosomal miR-21 decreased the expression of PDCD4." (PMID 33391543, 2021). "MiR-421 is able to target PDCD4 and regulate cell proliferation of breast cancer." (PMID 33686957, 2021). "IHC staining in breast tumors revealed that SKP2 overexpression promoted breast cancer cell proliferation in vivo, as determined by Ki-67 staining, and such promotion effect could be rescued by PDCD4 overexpression." (PMID 30760284, 2019). "On the other hand, Ki-67 staining showed SKP2 knockdown reduced breast cancer cell proliferation in vivo and such suppression effect could be rescued by PDCD4 knockdown." (PMID 30760284, 2019). "SKP2 promotes breast cancer tumorigenesis and radiation tolerance via PDCD4 degradation." (PMID 30760284, 2019). "PDCD4 plays important role in maintaining the stability of cell proliferation by keeping a normal rate of apoptosis and its decreased expression contributes to disease progression in breast cancer." (PMID 31798767, 2019). "In addition, miR-181b-5p is up-regulated in colorectal cancer and breast cancer by targeting programmed cell death 4 (PDCD4) and Bim, respectively." (PMID 31510100, 2019). "SKP2 was upregulated and PDCD4 was downregulated in breast cancer samples." (PMID 30760284, 2019). "Interestingly, we detected much lower levels of PDCD4 in TNBC cell lines with hyperactivated MAPK pathway than in the other breast cancer cell lines used in this study." (PMID 27028868, 2016). "In an orthotopic breast cancer model, co-expression of PDCD4 and PRMT5 accelerates tumor growth." (PMID 27556302, 2016). "MicroRNA-206 in mammary cancer stem-like cells (McCSCs) mediates Zinc-finger transcription factor Kruppel-like factor 4 (KLF4) pro-survival signaling through repression of the pro-apoptotic molecules programmed cell death 4 (PDCD4) and Cx43." (PMID 27229305, 2016). "When breast cancer cells with either wild-type (BT474) or activating mutations in both PI3K/Akt/mTORC1 and MAPK pathways (SUM159PT) were analyzed, we observed that the regulation of eIF4B, S6 and PDCD4 mostly relies on the agonist-stimulated pathway." (PMID 27028868, 2016).
breast cancer (continued). "As miR-21-5p overexpression increased cell growth, invasion and migration, and reduced apoptosis, through downregulation of several tumor suppressor genes such as PTEN, TPM1, and PDCD4, miR-21-5p is likely to be a true prognostic factor for breast cancer and other cancers." (PMID 27409424, 2016). "Interestingly, we identified PDCD4 as a new substrate for RSKs in breast cancer cells, which agreed with recently published results in melanoma cells." (PMID 27028868, 2016). "In breast cancer cells, PDCD4 caused an increased population in G0 to G1 phase without affecting other phases of cell cycle suggesting a potential role in apoptosis." (PMID 22272332, 2012). "In epithelial tumors, such as breast cancer, PDCD4 protein expression levels were slightly reduced in ductal carcinoma in situ, but markedly decreased in invasive ductal carcinoma, suggesting that its loss may be required for invasion." (PMID 20831814, 2010). "In addition, miR-27a, miR-96 and miR-182 could promote migration and invasion by the regulation of PTPN9 in breast cancer, and PDCD4 in hepatocellular cancer." (PMID 36539739, 2022). "However, whether the interplay between miR-21-5p and PDCD4 is involved in the Andro-induced inhibition of breast cancer growth and metastasis of luminal-like breast cancer remains undefined." (PMID 34249905, 2021). "We then explored whether SKP2 promotes breast cancer cells proliferation via PDCD4 suppression." (PMID 30760284, 2019). "Studies have reported that USP4 could inhibit breast cancer cell growth by upregulating PDCD4." (PMID 30335615, 2018). "Similarly, PDCD4 expression is blocked by miR-21 in breast cancer and colon cancer, suggesting that this interplay may be a general carcinogenic pathway, rather than a tissue-specific mechanism." (PMID 22200848, 2012). "Moreover, they also demonstrated that downregulation of PDCD4 in MCF-7 cells significantly alleviated the anti-proliferative effect of miR-21 inhibition, which suggests an essential role for PDCD4 as a mediator of the biological effects of miR-21 in breast cancer cells." (PMID 19473551, 2009). "A classic example is miR-21, which is frequently upregulated in breast cancer and is known to promote tumor growth and invasion by targeting tumor suppressor genes such as PTEN (phosphatase and TENsin homolog) and PDCD4 (programmed cell death protein 4)." (PMID 40244378, 2025). "For example, miR-21 facilitates breast cancer progression and metastasis by inhibiting tumor suppressor genes such as PTEN and PDCD4, which in turn activate the PI3K/AKT and MEK/ERK signaling pathways 38-41." (PMID 39479442, 2024). "HER2 activation downregulates PDCD4 through the MAPK and PI3K/AKT pathways, and overexpression of PDCD4 was reported to promote apoptosis in breast cancer cell lines in the presence of the HER2 inhibitor trastuzumab." (PMID 39268460, 2024). "By silencing miR-21, we prompted an increase in the onco-suppressor PDCD4 levels in MTC cell lines, as seen directly by other research groups in breast cancer cell lines and oral submucous fibrosis." (PMID 37361540, 2023). "This confirms that Emi1 KD can regulate the proliferation-related proteins PDCD-4, FasL, PTEN and RhoB in breast cancer cells." (PMID 38041032, 2023). "The PDCD-4, FasL, PTEN and RhoB genes have tumour-suppressing effects, and their expression is significantly reduced in malignant tumours, such as breast cancer and lung cancer." (PMID 38041032, 2023). "After the transfection of siEmi1, the mRNA levels of proliferation-related molecules PDCD-4, FasL, PTEN and RhoB in breast cancer cell strains were significantly reduced." (PMID 38041032, 2023). "In breast cancer, miR-21 can decrease PTEN and PDCD4 expression, whereas treatment with a miR-21 inhibitor combined with trastuzumab or doxorubicin can restore drug sensitivity." (PMID 35421166, 2022).
breast cancer (continued). "miR-421/PDCD4, miR-27a-3p/PD-L1, miR-424/PD-L1, miR-26a-5p/PDCD10 and miR-26b-5p/PDCD10 are other routes of participation of miRNAs in the pathogenesis of breast cancer." (PMID 35402235, 2022). "In breast cancer, GAS5 participates in the activation of proteins that include PTEN, PDCD4, DKK2, FOXO1, and SUFU through a ceRNA mechanism mediated by various miRNAs, including miR-21, miR-222, miR-221-3p, miR-196a-5p, and miR-378a-5p." (PMID 34202777, 2021). "This study demonstrated the participation of GAS5 in inhibiting the growth and invasion of breast cancer cells by binding oncogenic miR-21 and activating its targets, such as PTEN and PDCD4." (PMID 34202777, 2021). "Moreover, it has been indicated that PDCD4 can suppress metastasis in lung and breast cancer, suggesting that investigation of PDCD4-related pathway could have a potential in the prevention of breast cancer metastasis." (PMID 34359598, 2021). "The phosphorylation of PDCD4 at S76 by RSK is also reported by Cuesta and Holz using the Triple Negative Breast Cancer (TNBC) MDA-MB-231 cells." (PMID 31075975, 2019). "miR-21 is a well-studied oncomiR with anti-cancer targets, like PDCD4, TIMP3, and PTEN, and is overexpressed in human breast cancer tissues as compared to healthy breast tissues." (PMID 30214383, 2018). "In breast cancer, high PRMT5 expression, together with high PDCD4 (programmed cell death 4) levels predict overall poor survival." (PMID 29946150, 2018). "Overall, miR-21 functions as an oncomiR and modulates tumorigenesis through regulation of genes such as ANKRD46, BCL2, TIMP3, PDCD4, PTEN, TPM1, and MASPIN in breast cancer." (PMID 27746811, 2016). "This is exemplified by Programmed cell death 4 (PDCD4) protein in breast cancer, which shows increased tumorigenicity when over‐expressed with PRMT5 in an orthotopic model of breast cancer." (PMID 25475372, 2015). "mir21, as a master regulator of the metastatic processes was found to stimulate cell invasion by targeting tumor suppressors TPM1, PDCD4 and SERPINB5 in breast cancer or colon cancer." (PMID 24069219, 2013). "In breast cancer patients whose tumors contain high level of PRMT5, elevated PDCD4 expression correlates with a worse outcome." (PMID 23202904, 2012). "A previous publication reported that E2 can down-regulate miR-21 expression and thus increases the protein expression of miR-21 target genes programmed cell death 4 (PDCD4), PTEN and Bcl-2 in MCF-7 breast cancer cells." (PMID 22200848, 2012). "The PDCD4 levels varied in CTC in patients with breast cancer, and we found both PDCD4 positive and PDCD4 negative CTC in the blood of the same patient (n = 3)." (PMID 39890941, 2025). "Additionally, programmed cell death protein-4 (PDCD4) has been shown to decrease LOX expression in a HIF-independent manner, thereby mitigating the migration and invasion of breast cancer cells." (PMID 39247609, 2024). "Studies have reported that the programmed cell death receptor 4 (PDCD-4), fatty acid synthase ligand (FasL), PTEN and RhoB genes are related to the proliferative regulation of breast cancer cells and that Maspin, TIMP3 and RECK genes are related to the invasion regulation of breast cancer cells." (PMID 38041032, 2023). "For instance, programmed cell death protein 4 (PDCD4) is methylated at R110 by PRMT5 to inhibit its anti-tumor properties, and the co-expression of PDCD4 and PRMT5 generates a tumor-promoting phenotype in an orthotopic breast cancer model." (PMID 35216622, 2022). "Researchers have mentioned that in cervical cancer, miR-21 could facilitate cell proliferation by downregulating the expression of programmed cell death 4 (PDCD4) as well as in breast cancer." (PMID 36685972, 2022). "PDCD4 and its NAT partner, PDCD4-AS1, suppress breast cancer progression collaboratively." (PMID 32928281, 2020).
breast cancer (continued). "For example, treatment with anti-miR-21 oligonucleotides reduced breast cancer MCF-7 xenograft growth; therefore, PDCD4 might also be a new therapeutic target for cancer." (PMID 31620370, 2019). "PDCD4 (Programmed Cell Death Protein4) gene can be inhibited by miRNA-21 and results in the failure of programmed cell death, and finally enhances cell proliferation in HCC and breast cancer." (PMID 29254483, 2017). "Furthermore, high levels of PDCD4 and PRMT5 expression in breast cancer were correlated with poor patient outcome." (PMID 27556302, 2016). "Phosphorylation of eIF4B at S422, S6 at S235/236, 4E-BP1 at S65 as well as the decrease in PDCD4 levels mostly depended on the PI3K/Akt/mTORC1 pathway, under any tested condition, in breast cancer cell lines in which only this pathway was up-regulated (MCF7, T47D, and MDA-MB-468)." (PMID 27028868, 2016). "Furthermore, both PTEN (rs = −0.502; p = 0.005) and PDCD4 (rs = −0.426; p = 0.019) protein expression significantly and inversely correlated with the expression of miR-21 in HER2-positive breast cancer patients." (PMID 26452030, 2015). "In addition, p70S6K plays an important role in metastasis by regulating key proteins such as cyclin D1, PDCD4 and FAK, whereas E-cadherin, β-catenin and TG2 are essential for cell attachment, survival, and invasion, as well as metastasis in breast cancer." (PMID 25333576, 2015). "Thus far, two direct miR-21 target genes have been experimentally verified in breast cancer, i.e. TM1 and PDCD4." (PMID 19473551, 2009). "Additionally, miR-21 links EMT and inflammatory signals (IL-6/STAT3/NF-κB-mediated signaling loop and activating the PI3K pathway) to confer resistance to trastuzumab and chemotherapy in HER2-positive breast cancer patients through downregulation of PTEN and programmed cell death 4 (PDCD4)." (PMID 31766744, 2019). "SKP2 and PDCD4 showed negative correlation in human breast cancer tissues." (PMID 30760284, 2019). "In contrast to data showing the importance of PDCD4 as a functional relevant target of miR-21 in breast cancer cells as well as in colon cancer, in the osteosarcoma-derived cell line MG63 we failed to observe an influence of augmented miR-21 expression on PDCD4." (PMID 27513462, 2016). "We show that RSKs regulate the activities of the translation initiation factor eIF4B and the translational repressor PDCD4 in TNBC cells with up-regulated MAPK pathway, but not in breast cancer cells with hyperactivated PI3K/Akt/mTORC1 pathway." (PMID 27028868, 2016).